ADAM17 (ADAM metallopeptidase domain 17)
Diseases named in the same sentence as ADAM17 in open-access papers (continued):
Sharing a sentence is not in itself a finding about the gene and the disease.
SARS-CoV infection (8 papers, 2020 to 2023). "What is particularly interesting is that such cleavage of ACE2 by proteases, especially by ADAM-17, is activated in SARS-CoV infection." (PMID 37560522, 2023). "Active TACE/ADAM17 facilitates SARS-CoV infection, but soluble ACE2 is dispensable for replication of SARS-CoV and NL63." (PMID 32629875, 2020). "The cleavage of ACE2 by ADAM-17 is activated in SARS-CoV infection, generating sACE2." (PMID 37560522, 2023). "Intriguingly, both SARS-CoV infection and concomitant TNF-α secretion were significantly attenuated not only by knock-down of ADAM17/TACE expression by siRNA but also by deletion of the ACE2 cytoplasmic tail which is responsible for ADAM17/TACE activation." (PMID 32708755, 2020). "The differential proteolysis of ACE2 could also be attributed to i) a differential requirement of ADAM17 during infection, since silencing of ADAM17 significantly reduced SARS-CoV infection but not HNL-63-CoV, and ii) the differential cellular microenvironment requirements for processing S protein." (PMID 34163462, 2021).
systemic lupus erythematosus (8 papers, 2014 to 2025). An autoimmune multi-organ disease typically associated with vasculopathy and autoantibody production. "IFN-κ, an IFN-I that is highly expressed by lupus keratinocytes, reduced LC ADAM17 sheddase activity by nearly 40% when used to treat LCs ex vivo." (PMID 38860651, 2024). "While LC ADAM17 protein levels were not consistently affected and LC numbers were unchanged in the three lupus models examined, LC ADAM17 sheddase activity was consistently reduced." (PMID 38860651, 2024). "Lastly, we show that UVR-induced reactive oxygen species (ROS) known to promote ADAM17 sheddase activity, was reduced in lupus model LCs, that anti-IFNAR restored ROS expression, and that ROS was of cytoplasmic origin." (PMID 38860651, 2024). "Here, we sought to understand how the lupus skin environment contributes to LC ADAM17 dysfunction and, in the process, differentiate between effects on LC ADAM17 sheddase function, LC ADAM17 expression, and LC numbers." (PMID 38860651, 2024). "Particularly, ADAM17 (P78536) plays an important role in several human inflammatory autoimmune diseases, such as rheumatoid arthritis, multiple sclerosis, and systemic lupus erythematosus." (PMID 37492575, 2023). "We asked whether IFN-I was an important regulator of LC ADAM17 function in lupus models." (PMID 38860651, 2024). "That anti-IFNAR reduction of photosensitive responses across two lupus models depended on EGFR signaling and LC ADAM17 provided strong support for the idea that IFN-I contributes to photosensitivity at least in part by promoting LC ADAM17 sheddase dysfunction." (PMID 38860651, 2024). "Reactive oxygen species (ROS) is a known mediator of ADAM17 activity; we show that UVR-induced LC ROS production is reduced in lupus model mice, restored by anti-IFNAR, and is cytoplasmic in origin." (PMID 38860651, 2024). "Renal dysfunction is often a consequence of the autoimmune disease systemic lupus erythematosus (SLE), and ADAM17 substrates TNFα and heparin-binding EGF (HB-EGF) have been implicated as important mediators of this condition called lupus nephritis (LN)." (PMID 30890028, 2019). "We have previously shown that Langerhans cells (LCs) limit keratinocyte apoptosis and photosensitivity via a disintegrin and metalloprotease 17 (ADAM17)-mediated release of epidermal growth factor receptor (EGFR) ligands and that LC ADAM17 sheddase activity is reduced in lupus." (PMID 38860651, 2024). "IFN-I inhibits LC ADAM17 sheddase activity in murine and human LCs, and IFNAR blockade in lupus model mice restores LC ADAM17 sheddase activity, all without consistent effects on LC ADAM17 protein expression or LC numbers." (PMID 38860651, 2024). "For example, this could reflect an increased activity in lupus blood, of specific proteases, such as ADAM10 and ADAM17 (TNF-α-converting enzyme, TACE), which are capable of enzymatically converting membrane-bound Mer to soluble Mer." (PMID 24650765, 2014). "Together, these data suggesting that anti-IFNAR restored LC ADAM17 sheddase function in non-lesional skin across three distinct SLE models pointed toward a scenario whereby the IFN-I-rich environment in non-lesional lupus skin inhibits LC ADAM17 sheddase function." (PMID 38860651, 2024). "Together, our results establish that multiple photosensitive murine SLE models are similar to human lupus patients in demonstrating IFN signatures in non-lesional skin and put forth a mechanism whereby IFN-I contributes to photosensitivity at least in part by inhibiting LC sheddase ADAM17 activity." (PMID 38860651, 2024).
autoimmune disease (7 papers, 2010 to 2025). A disorder resulting from loss of function or tissue destruction of an organ or multiple organs, arising from humoral or cellular immune responses of the individual to their own tissue constituents. "Furthermore, we suggest a series of events where enhanced ADAM17 activity increases Mer inactivation and depresses Mer signaling, thus removing protection against the loss of self-tolerance and the onset of autoimmune disease in SjSS mice." (PMID 34575873, 2021). "ADAM17 has attracted considerable interest as a key enzyme in autoimmune disease pathogenesis since it is responsible for the release of soluble TNF-α." (PMID 39768182, 2024). "In recent years, the dysregulated expression of ADAM17 was considered the driver of several pathological conditions, including autoimmune diseases." (PMID 39768182, 2024). "The following paragraphs will explore the most recent findings related to ADAM17-dependent pathways activated in autoimmune diseases." (PMID 39768182, 2024). "A correlation has been identified between the overexpression of ADAM17 and the degree of fibrotic evolution in patients with degenerative fibrotic evolution of autoimmune diseases." (PMID 39768182, 2024). "There are several approaches being used to pharmacologically inhibit ADAM17 in various diseases from infection to autoimmune diseases and cancer." (PMID 35215094, 2022). "Conversely, the role of ADAM17 has been extensively evaluated in several autoimmune diseases, and this molecule has been shown to be located at the crossroads of various molecular pathways involved in the transcription and translation of pro-inflammatory factors." (PMID 41517433, 2025). "Overall, TNF-α, IL-1β, and IL-6 could be valid molecular targets in light of their deregulation in autoimmune diseases and their involvement as activators of transduction cascades involving ADAM17." (PMID 39768182, 2024). "As part of all these discoveries that improve knowledge of the mechanisms in which ADAM17 plays a fundamental role as an activator of traditional cascades, our interest lies in autoimmune diseases, which represent a thriving field of research, given the impact on the health of patients." (PMID 39768182, 2024). "More recently, investigations were warranted to assess the role of ADAM17 inhibitors in autoimmune diseases since elevated expression and/or activation levels of ADAM17 were observed in biopsies of patients affected by autoimmune diseases such as IPF, Crohn’s disease, RA, and psoriasis." (PMID 39768182, 2024). "Another autoimmune disease in which the role of ADAM17 in EMT-dependent fibrosis is recognized, albeit indirectly, is SSc, characterized by an evolution of fibrotic tissue in various organs affecting the instrumental, cardiovascular, urinary, and respiratory systems." (PMID 39768182, 2024). "The extent of autoimmune disease in Aire KO mice is dependent on the genetic background, with very mild disease observed on the mixed 129xB6 background (which incidentally, is the same background as the Adam17/Foxn1 mice used in our studies)." (PMID 20976004, 2010). "In this paragraph, we will report the most recent discoveries on the involvement of ADAM17 in molecular features characterizing autoimmune diseases; this could help to guarantee the identification of common pathways based on which new therapeutic perspectives can germinate." (PMID 39768182, 2024). "In light of the latest discoveries on the roles played by ADAM17 in the pathogenetic mechanisms of autoimmune diseases, which we have discussed extensively in this review, an update on the role of ADAM17 in the phenomenon of epithelial-to-mesenchymal transition (EMT) could not be missed." (PMID 39768182, 2024). "In this section, we will analyze the most recent discoveries, analyzing the correlation between ADAM17 and NOTCH signaling in autoimmune diseases." (PMID 39768182, 2024).
autoimmune disease (continued). "The activation of the ADAM17/AREG axis has been demonstrated in various inflammatory conditions and in various autoimmune diseases, characterized by a chronic inflammatory state." (PMID 39768182, 2024). "However, the actual molecular bridges that connect ADAM17 to EMT remain to be clarified, and, above all, it is of primary interest to evaluate these mechanisms in other autoimmune diseases." (PMID 39768182, 2024). "Adam17/Foxn1 mice do not display any overt phenotypes that would indicate autoimmune disease, which is consistent with the normal thymic phenotype and production of mature T cells observed in two-to-three-month-old Aire KO mice." (PMID 20976004, 2010).
cardiomyopathy (7 papers, 2014 to 2026). A disease of the heart muscle or myocardium proper. "We also demonstrate that a human disease-associated iRhom1 mutation linked to cardiomyopathy disrupts ADAM17 maturation and trafficking." (PMID 42024498, 2026). "For example, mutations in ADAM17 not only cause inflammatory skin and bowel disease but increased susceptibility to infection and cardiomyopathy." (PMID 25093584, 2014). "The therapeutic effect and its mechanism of cardiomyocyte-specific ADAM17 deficiency on doxorubicin-induced cardiomyopathy, and whether it interferes with the anti-tumor effects of doxorubicin have not been reported." (PMID 39406701, 2024). "Besides ADAM17 inducing cardiomyopathies via exacerbating inflammatory responses and lipids dysregulation, its variants and mutants have been associated with mild cardiomyopathies and congenital heart defects, including Tetralogy of Fallot." (PMID 34150874, 2021). "To ascertain the role of ADAM17 in doxorubicin-induced cardiomyopathy, we selected A17fl/fl and A17α-MHCKO male mice at 8 weeks of age and injected doxorubicin into these mice in the second proportion of in vivo experiments." (PMID 39406701, 2024). "There were few studies in the literature on the role of ADAM17 in the pathogenesis of cardiomyopathy." (PMID 39406701, 2024). "In the present study, we indisputably demonstrated that ADAM17 expression and activity were significantly increased in a mouse model of doxorubicin-induced cardiomyopathy." (PMID 39406701, 2024). "This study was carried out to test our hypothesis that ADAM17 aggravates cardiomyocyte apoptosis induced by doxorubicin and inhibition of ADAM17 may ameliorate doxorubicin-induced cardiomyopathy." (PMID 39406701, 2024). "However, the reason why ADAM17 expression and activity were elevated in doxorubicin-induced cardiomyopathy was unknown." (PMID 39406701, 2024). "Thus, ADAM17 deficiency reduced cardiomyocyte apoptosis in doxorubicin-induced cardiomyopathy probably not by improving autophagy." (PMID 39406701, 2024). "However, the protein and mRNA expression levels of ADAM17 were dramatically decreased in the siC/EBPβ + DOX group versus the siNC + DOX group, suggesting that C/EBPβ might be an upstream mediator of ADAM17 upregulation in mice with doxorubicin-induced cardiomyopathy." (PMID 39406701, 2024). "The mechanism of ADAM17 enhancing TRAF3 expression in doxorubicin-induced cardiomyopathy has not been clarified." (PMID 39406701, 2024). "Importantly, ADAM17 knockdown attenuates doxorubicin-induced cardiomyopathy without compromising the antitumor efficacy of doxorubicin." (PMID 41050403, 2025).
diabetic cardiomyopathy (7 papers, 2022 to 2024). Diabetic cardiomyopathy is a disorder of the heart muscle in people with diabetes. "In mice with diabetic cardiomyopathy, inhibition of ADAM17 ameliorated fibrosis and apoptosis, whereas ADAM17 deficiency increased cell viability." (PMID 36733457, 2023). "Proposed mechanisms underlying the salutary effects of ADAM17 deficiency on diabetic cardiomyopathy." (PMID 35909160, 2022). "Taken together, our findings highlight the potential translational value of ADAM17 inhibition in combination with eplerenone after diabetic cardiomyopathy." (PMID 38799171, 2024). "Several small molecule inhibitors of ADAM17 have been screened for cancer research, which provides conditions for the future development of ADAM17 small molecule inhibitors for diabetic cardiomyopathy, with great clinical translational potential." (PMID 38799171, 2024). "A disintegrin and metalloprotease domain family protein 17 (ADAM17) is a new member of renin-angiotensin system (RAS) but its role in the pathogenesis of diabetic cardiomyopathy (DCM) is obscure." (PMID 36313337, 2022). "In addition, the findings suggest that the lncRNA GAS5/miR-21-5p axis may serve as a candidate therapeutic target for diabetic cardiomyopathy, while another study found that inhibition of ADAM17 may provide a promising approach." (PMID 37821982, 2023). "Apart from that, increased ADAM17 activity was also found in patients with acute myocarditis, and hypertrophic cardiomyopathy or dilated cardiomyopathy (DCM), as well as in mice with diabetic cardiomyopathy." (PMID 36733457, 2023). "Angiotensin-converting enzyme 2 (ACE2) has proven beneficial in attenuating diabetic cardiomyopathy (DCM) but has been found to be a substrate of a disintegrin and metalloprotease protein-17 (ADAM17)." (PMID 35909160, 2022). "Thus, ADAM17 inhibition reduced collagen I, collagen III and TGF-β1 expression, and ameliorated cardiac fibrosis in diabetic cardiomyopathy." (PMID 36313337, 2022).
psoriasis (7 papers, 2014 to 2024). An autoimmune condition characterized by red, well-delineated plaques with silvery scales that are usually on the extensor surfaces and scalp. "Considering the high levels of ADAM17 found in psoriatic patients, this protease has become an important therapeutic target, having a crucial role in the pathogenesis of psoriasis." (PMID 39768182, 2024). "Over-expression of miR-21 has been demonstrated in skin abrasions of patients with psoriasis and in association with down-regulation of TIMP-3 expression and stimulation of TACE/ADAM17." (PMID 32695942, 2020). "In addition, ADAM17 inhibitors were considered for the topical treatment of psoriasis because of their effect on T-cell-mediated immune response in psoriasis plaques." (PMID 39768182, 2024).
Stroke (7 papers, 2012 to 2024). Sudden impairment of blood flow to a part of the brain due to occlusion or rupture of an artery to the brain. "Taken as a whole, these collective observations provided associative evidence supporting our hypothesis that stroke induces a peripheral rise in sCD163 levels via increased ADAM17 activity." (PMID 29021532, 2017). "The ML disease pathways analysis shows that ADAM17 activation promotes memory deficits, bullous pemphigoid, deterioration of connective tissue, stroke and human diseases." (PMID 38341954, 2024). "A locus in ADAM23 has been shown to correlate with stroke outcome, and in our study multiple ADAM gene family members such as ADAM9, ADAM17, ADAM19 were associated with poor stroke outcomes." (PMID 36691064, 2023). "In stroke patients, peripheral blood ADAM17 activity and soluble CD163 levels are elevated, whereby CD163 can be shed from the plasma membrane via the metalloprotease ADAM17 to generate a soluble peptide with lympho-inhibitory properties." (PMID 34201498, 2021). "Peripheral blood ADAM17 activity and soluble CD163 levels were elevated in stroke patients relative to non-stroke control groups, and negatively associated with post-stroke lymphocyte counts." (PMID 29021532, 2017). "Next, we wanted to determine the direct effects of the post-stroke peripheral inflammatory milleu on ADAM17-mediated sCD163 shedding by peripheral innate immune cell populations." (PMID 29021532, 2017). "Taken together, these results indicate that ECM-degrading enzymes, that is, MMPs and ADAM-17, worsen the functional disturbance after stroke by promoting deconstruction of the blood-brain barrier and infiltration of the inflammatory cells." (PMID 22420304, 2012). "Notably, a compound variable, indexing ADAM17 mRNA expression, CD163 mRNA expression, and cellular TACE activity was correlated with worse National Institute of Health Stroke Severity (NIHSS) scores." (PMID 33498620, 2021). "A perfect example in this regard is the fact that ADAM17 inhibitors are often cited as a potential stroke therapeutic under the premise that they could ultimately limit excessive innate-driven inflammation and its associated complications via a reduction in TNFα production." (PMID 29021532, 2017). "Furthermore, other groups have reported heightened ADAM17 activity in animal models of ischemic brain injury, as well as stroke-induced increases in peripherally circulating levels of other ADAM17 substrates such as tumor necrosis factor alpha (TNFα) in human subjects." (PMID 29021532, 2017). "Subsequent in vitro experiments suggested that this stroke-induced elevation in circulating soluble CD163 likely originates from activated monocytic cells, as serum from stroke patients stimulated ADAM17-dependant CD163 shedding from healthy donor-derived monocytes." (PMID 29021532, 2017). "ADAM17 activity did appear to be elevated in neutrophil cultures treated with serum obtained from ischemic stroke patients relative to those treated with serum obtained from both neurologically asymptomatic controls and stroke mimics, however this increase was not statistically significant." (PMID 29021532, 2017).
fibrosis (6 papers, 2021 to 2025). the formation of excess fibrous connective tissue in an organ or tissue in a reparative or reactive process. "Fibrosis mediated by ADAM17 has been identified as an important contributor, although the specific relationship between its multiple regulatory functions and the pathogenesis is unclear." (PMID 40224489, 2025). "In conclusion, ADAM17 knockdown attenuates while ADAM17 overexpression aggravates cardiac fibrosis via regulating ACE2 shedding and myofibroblast transformation through TGF-β1/Smad3 signaling pathway in diabetic mice." (PMID 36313337, 2022). "Meanwhile, ADAM17 mRNA and protein levels were significantly higher in fibrosis hearts than in normal hearts." (PMID 34035876, 2021). "Furthermore, ADAM17–EGFR promotes dermal fibrosis in SSc mice in conjunction with increased inflammation caused by phorbol 12-myristate 13-acetate (PMA) in skin fibroblasts." (PMID 40224489, 2025). "Moreover, TGF-β signaling has been shown to be involved in ADAM17 upregulation and increased airway fibrosis." (PMID 39682757, 2024).
head and neck cancer (6 papers, 2011 to 2023). A primary or metastatic malignant neoplasm affecting the head and neck. "Although the exact mechanism remains largely unclear, there is some evidence to suggest that upregulated ADAM17 in head and neck cancer plays key roles in tumour initiation and progression via proteolytic and/or adhesive properties." (PMID 32236893, 2020). "Furthermore, miR-224, miR-148a-3p, and miR-449b-3p can modulate ADAM17 expression in head and neck cancer to suppress malignancy." (PMID 37175410, 2023). "miR145 could target the SOX9/ADAM17 axis and inhibit tumor-initiating cells and IL-6-mediated paracrine effects in head and neck cancer." (PMID 24941171, 2014).